ISM1 (isthmin 1)
Diseases named in the same sentence as ISM1 in open-access papers (continued):
Sharing a sentence is not in itself a finding about the gene and the disease.
emphysema (6 papers, 2022 to 2024). "Adiponectin-deficient mice presented heightened allergic airway inflammation and spontaneous emphysema, phenotypes similar to those of ISM1-deficient mice." (PMID 37932719, 2023). "As ISM1 deficiency results in lung inflammation and emphysema and ISM1 expression in the lung is upregulated by intratracheal LPS instillation, we wish to examine the role of ISM1 in acute lung inflammation in response to intratracheally instilled LPS (2 mg/kg) using Ism1−/− and wild-type mice." (PMID 35752760, 2022). "In another study, a deficiency of isthmin 1 (ISM1) in mice led to an increase in the functional heterogeneity and recruitment of AMs, resulting in enhanced pulmonary inflammatory responses, emphysema, and impaired lung function." (PMID 38891820, 2024). "Nevertheless, the emphysema phenotype is consistent with that in Ism1−/− FVB/N mice and has been attributed to more AMs being in the activated proinflammatory state." (PMID 37932719, 2023). "ISM1 knockout mice (Ism1-/-) show increased functional heterogeneity in AMs, with enduring lung inflammation and progressive emphysema, similar phenotypes to those in human COPD." (PMID 38203236, 2023). "SERPINF1 and ISM1 protect against emphysema formation, whereas AQP1 promotes eosinophilic infiltration." (PMID 38203236, 2023). "Regarding the genes regulating angiogenesis, SERPINF1 and ISM1 upregulation protect against emphysema formation, whereas AQP1 upregulation promotes eosinophil infiltration." (PMID 38203236, 2023). "Recently, we also reported that ISM1 is an anti-inflammatory protein in the lung with Ism1-/- mice presenting spontaneous chronic low-grade lung inflammation and obvious emphysema at young adult stage." (PMID 35752760, 2022). "Focal areas of alveolar epithelial hyperplasia, thickening of the alveolar septa as well as emphysema were obvious in Ism1−/− mice." (PMID 35752760, 2022). "Notably, Adipoq−/− mice also present spontaneous emphysema phenotype similar to ISM1−/− mice in early adulthood." (PMID 37932719, 2023). "Notably, we observed spontaneous emphysema phenotype in ISM1−/− mouse lungs consistent with our earlier findings, suggesting that the pre-existence of lung inflammation in the absence of ISM1 could potentiate the airway response against the allergen." (PMID 37932719, 2023). "ISM1 protects lung homeostasis via cell-surface GRP78-mediated alveolar macrophage apoptosis, specifically, rISM1 effectively quenches lung inflammation while ISM1−/−mice develop spontaneous emphysema." (PMID 35958402, 2022). "In conjunction with our previous report that ISM1−/− lungs harbor more activated pro-inflammatory AMs and trigger spontaneous emphysema, our findings here showed that HDM challenge generated a more severe allergic airway inflammation with pre-existing emphysema." (PMID 37932719, 2023). "Furthermore, Ism1 knockout in mice exhibited an increase in cs-GRP78high AMs along with upregulation of MMP9, MMP12, and NF-κB p65, in addition to a moderate increase in TGF-β1 and VEGF-A, prolonged lung inflammation, and progressive emphysema." (PMID 36611811, 2022).
hepatocellular carcinoma (6 papers, 2020 to 2024). A malignant tumor that arises from hepatocytes. "Specific examples include hsa_circ_0091570, which acts as a competitive endogenous RNA (ceRNA) for miR-1307, elevating ISM1 expression and thereby influencing hepatocellular cancer progression." (PMID 38395751, 2024). "In summary, ISM1 upregulation and overexpression are reported in multiple cancers, including gastric cancer, hepatocellular carcinoma (HCC), colon adenocarcinoma, and colorectal cancer, while ISM2 overexpression was reported in choriocarcinoma." (PMID 36611811, 2022). "Another research found hsa_circ_0091570 can sponge miR‐1307 to regulate ISM1 expression which works in hepatocellular cancer (HCC) progression." (PMID 33094914, 2020).
Hepatic steatosis (5 papers, 2023 to 2025). Steatosis is a term used to denote lipid accumulation within hepatocytes. "Notably, recombinant Ism1 alleviates hepatic steatosis by suppressing SREBP-1c in a diet-induced fatty liver mouse model and ameliorates diabetes in diet-induced obese mice." (PMID 40243151, 2025). "Remarkably, while the glucoregulatory function of the novel adipokine is shared with insulin, ISM1 also neutralizes lipid accumulation in the liver by inhibiting de novo lipogenesis, promoting protein synthesis and preventing hepatic steatosis in a diet-induced fatty liver mouse model." (PMID 36595188, 2023). "Elevated ISM1 expression may serve as an indicator of fibrotic burden and disease progression in chronic hepatitis B. However, to date, studies exploring the role of ISM1 in chronic hepatitis B are lacking; current literature is largely restricted to its involvement in hepatic steatosis." (PMID 41462970, 2025).
Insulin resistance (5 papers, 2022 to 2025). Increased resistance towards insulin, that is, diminished effectiveness of insulin in reducing blood glucose levels. "In conclusion, our findings demonstrated an association between T2D and increased insulin resistance with reduced Ism1 levels." (PMID 39857685, 2025). "It is plausible that Ism1 levels are altered in response to fasting and feeding, insulin resistance, or aging – conditions associated with temporary or chronic muscle loss." (PMID 36169399, 2022). "Furthermore, reduced Akt is associated with skeletal muscle insulin resistance, in line with our previous observation that Ism1-KO mice fed a high-fat diet are more insulin resistant." (PMID 36169399, 2022). "Herein, we found that cardiac-specific overexpression of ISM1 significantly mitigated insulin resistance by promoting glucose uptake in aging mice." (PMID 38300636, 2024). "We recently reported that the adipocyte-secreted protein isthmin-1 (Ism1) improves glucose tolerance and insulin resistance by phosphorylating AktS473, which mediates increased adipose and skeletal muscle glucose uptake." (PMID 36169399, 2022). "Among the 10 most upregulated genes in NAFLD were genes related to insulin resistance (PRKCE), glucose metabolism and steatosis (PLIN1), glucose uptake regulation (ISM1), oxidative cell stress response (TP53INP1), and a proinflammatory marker (SERPINE 1)." (PMID 40489530, 2025). "A novel adipokine known as Isthmin-1 (ISM1) plays a crucial role in aging-related cardiac dysfunction; overexpression of the ISM1 in aging mice mitigates insulin resistance via promoting glucose uptake." (PMID 41567643, 2025). "Additionally, individuals with higher CAP scores demonstrated significantly lower Ism1 levels, and the Spearman’s rank correlation revealed a negative association between Ism1 and both CAP scores (r = −0.109, p-value = 0.025) and insulin resistance (r = −0.141, p-value = 0.004)." (PMID 39857685, 2025).
type 2 diabetes (5 papers, 2022 to 2025). "To visualize the risk of ISM1 and type 2 diabetes, we created a nomogram." (PMID 35712241, 2022). "Logistic regression analysis indicated that the serum Ism1 level was an independent protective factor of type 2 diabetes (OR=0.69, 95%CI: 0.54-0.89)." (PMID 35712241, 2022). "Moreover, despite a small sample size, ISM1 was proven to be detectable in the circulation and was reported to be lower in patients with type 2 diabetes than in those with normoglycemic control." (PMID 39119006, 2024).
colon cancer (3 papers, 2021 to 2025). "The ISM1 level in colon cancer cell lines was higher than that in the normal colon epithelial cell line, which was consistent with previous results showing that the ISM1 expression level is higher in CRC tissues than in normal tissues." (PMID 34350177, 2021). "We also found that ISM1 KD significantly impaired the proliferation ability of colon cancer cells." (PMID 34350177, 2021). "We then employed si-ISM1-1 and si-ISM1-3 in the ISM1-high colon cancer cell lines LoVo and DLD1." (PMID 34350177, 2021). "Moreover, ISM1 KD significantly impaired the migration and proliferation abilities of colon cancer cells." (PMID 34350177, 2021). "We first detected ISM1 expression levels in a human normal colon epithelial cell line (NCM460) and in colon cancer cell lines (LoVo, HCT116, HT29, DLD1, SW480, and SW620)." (PMID 34350177, 2021). "ISM1 promoted EMT and colon cancer cell migration and proliferation." (PMID 40302814, 2025). "Notably, through in vitro experiments, we found that ISM1 promoted EMT and colon cancer cell migration and proliferation." (PMID 34350177, 2021).
colorectal cancer (3 papers, 2021 to 2025). A primary or metastatic malignant neoplasm that affects the colon or rectum. "ISM1 has been related to clefting and craniofacial patterning and colorectal cancer and probably plays a role in the negative regulation of angiogenesis." (PMID 37891789, 2023). "Moreover, recent studies have shown that ISM1 is significantly overexpressed in colorectal cancer (CRC) tissues and in the blood of patients, correlating with poor prognosis." (PMID 40572169, 2025).
gastric cancer (3 papers, 2015 to 2022). A primary or metastatic malignant neoplasm involving the stomach. "Another study demonstrated that ISM1 is a binding protein of lncRNA H19, which mediates ISM1 upregulation and boosts carcinogenesis and metastasis of gastric cancer." (PMID 36611811, 2022). "A previous study indicated that the effect of H19 on gastric cancer was mediated by direct up-regulation of ISM1, which is a binding protein of H19." (PMID 25944697, 2015).
Hyperglycemia (3 papers, 2023 to 2024). An increased concentration of glucose in the blood. "Significant association of ISM1 with post-challenge hyperglycemia exists only in men." (PMID 39119006, 2024). "ISM1 has been recently identified in mouse and human adipocytes, regulating glucose uptake while suppressing hepatic lipid synthesis, thus improving hyperglycemia and reducing lipid accumulation in mouse models." (PMID 36595188, 2023). "Circulating ISM1 serves as a potential biomarker for post-challenge hyperglycemia in men." (PMID 39119006, 2024). "Moreover, when using a broader definition of 2 h post-challenge hyperglycemia without considering the level of fasting glucose, the inverse association of ISM1 and risk for PH remained significant only in men (n=522)." (PMID 39119006, 2024).
melanoma (3 papers, 2021 to 2023). A malignant, usually aggressive tumor composed of atypical, neoplastic melanocytes. "Stable overexpression of ISM1 in B16 melanoma inhibited tumor growth in mice by suppressing tumor angiogenesis, and knockdown of ISM1 in zebrafish embryos caused abnormal formation of trunk intersegmental vessels." (PMID 36995541, 2023).
adrenal tumors (2 papers, 2019 to 2022). "Researchers have found that the expression level of ISM1 was significantly upregulated in both CTNNB1 mutated adrenal tumors and CTNNB1 mutated adrenal lesions, suggesting that ISM1 may be a potential therapeutic target for CTNNB1 mutation-related adrenal disease." (PMID 35958402, 2022).
allergic asthma (2 papers, 2023 to 2024). A asthma with a basis in a pathological type I hypersensitivity reaction. "This presents ISM1 as a mediator of cellular interaction and a potential therapeutic tool in allergic asthma." (PMID 38686182, 2024). "Teeet al. presented valuable insight into the anti-inflammatory role of isthmin-1 (ISM1) in allergic asthma, whose function has been described for other conditions." (PMID 38686182, 2024). "Reduced AM efferocytosis under ISM1 deficiency likely led to increased secondary necroptosis, resulting in more severe inflammation in ISM1−/− mice in HDM-induced allergic asthma." (PMID 37932719, 2023). "To investigate the role of ISM1 in allergic asthma, we conducted a study using HDM-induced allergic-like airway/lung inflammation in ISM1−/− and wild-type (WT) mice." (PMID 37932719, 2023). "Both total IgE and HDM-specific IgE levels in the sera were significantly higher in ISM1−/− mice under HDM-induced allergic asthma than those of the WT mice." (PMID 37932719, 2023). "We then intratracheally administered either CHO-derived rISM1 or vehicle to both ISM1−/− and WT mice in the HDM-induced allergic asthma model." (PMID 37932719, 2023).
colon adenocarcinoma (2 papers, 2022 to 2024). "miR-1307–3p has low expression levels in colon adenocarcinoma tissues and cell lines, can regulate proliferation and apoptosis of colon adenocarcinoma cells via targeting ISM1 and regulating activation of Wnt3a/β-catenin signaling pathway." (PMID 39305404, 2024).
fibrosis (2 papers, 2022 to 2025). the formation of excess fibrous connective tissue in an organ or tissue in a reparative or reactive process. "In the evaluation of histoscores obtained from immunohistochemical staining for PODXL, PTX3, and ISM1, a statistically significant difference was observed between liver tissues with fibrosis associated with chronic hepatitis B and those from the control group." (PMID 41462970, 2025). "Altogether, these results indicate that ISM1 deficiency led to a heightened lung inflammatory response to intratracheal delivered LPS, leading to abnormal lung repair and intensified post-ALI fibrosis in mice." (PMID 35752760, 2022). "Furthermore, when compared to the low-grade fibrosis group, a statistically significant increase in ISM1 immunoreactivity was observed in the high-grade fibrosis group (p = 0.016)." (PMID 41462970, 2025).
gestational hypertension (2 papers, 2020 to 2022). "The serum levels of ISM1 protein were measured in 30 patients with normotensive pregnancy, 21 patients with gestational hypertension and 30 patients with preeclampsia." (PMID 33088937, 2020). "Placentas from gestational hypertension displayed high intensity for ISM1 antibody in about 97% of the trophoblastic cells, and in preeclamptic placentas ISM1 antibody exhibited expression in 95% of the cells with strong intensity." (PMID 33088937, 2020). "The level of ISM1 in the control group was 0.8–6.7 ng/mL (median 2.6 ng/mL), in the gestational hypertension group was 0.8–3.6 ng/mL (median 2.68 ng/mL) and in the preeclampsia group was 1.2–4.4 ng/mL (median 2.5 ng/mL)." (PMID 33088937, 2020). "We performed immunohistochemistry of ISM1 in placenta tissues from normotensive, gestational hypertension and preeclampsia pregnancies and confirmed the serum results." (PMID 33088937, 2020). "We compared the immunohistochemistry of ISM1 and found that nonrelevant difference was exhibited among the staining in normal, gestational hypertension and preeclamptic placentas." (PMID 33088937, 2020).
Nonalcoholic Fatty Liver Disease (2 papers, 2022 to 2023). "The decrease of Ism1 level did not increase the risk of non-alcoholic fatty liver disease in diabetic patients by Binary logistic regression analysis (OR=1.08, 95% CI: 0.69-1.69)." (PMID 35712241, 2022).
rheumatoid arthritis (2 papers, 2021 to 2025). A chronic, systemic autoimmune disorder characterized by inflammation in the synovial membranes and articular surfaces. "Although ISM1 has been implicated in chronic inflammatory conditions, its clinical relevance in rheumatoid arthritis (RA) remains unknown." (PMID 40506888, 2025). "Other three hyperdynamic CpGs common across four samples, as well as that in ISM1, were reported as EWAS markers of several traits of air-pollution (PM 2.5), rheumatoid arthritis, infertility (studies on sperm), exercise, and Kabuki syndrome." (PMID 34903243, 2021).
steatosis (2 papers, 2025). Increased lipid within the cytoplasm of cells. "They demonstrate that Ism1 is a secreted polypeptide hormone that regulates adipose tissue glucose uptake while reducing steatosis in the liver." (PMID 40142334, 2025).
adrenocortical tumours (1 paper, 2024). "Both AFF3 and ISM1 are known to be overexpressed in benign and malignant adrenocortical tumours with CTNNB1 mutation." (PMID 39167619, 2024). "Of note, in the two samples with an abundance of AC1, we have observed a high expression of AFF3, ISM1 and LEF1, all known CTNNB1 target genes in both benign and malignant adrenocortical tumours." (PMID 39167619, 2024).
airway hyperresponsiveness (1 paper, 2023). "Accordingly, our results showed that ISM1 deficiency significantly enhanced airway hyperresponsiveness (AHR), a pathological feature of asthma." (PMID 37932719, 2023). "Reduced adiponectin expression under ISM1 deficiency also contributed to intensified necroptosis, prolonged inflammation, and heightened severity of airway hyperresponsiveness." (PMID 37932719, 2023). "Our findings indicate that ISM1 deficiency exacerbates airway inflammation and airway hyperresponsiveness (AHR), whereas intratracheal (i.t.)delivery of recombinant ISM1 (rISM1) attenuates HDM-induced airway inflammation." (PMID 37932719, 2023).
asthma (1 paper, 2023). "While ISM1 expression has a bimodal distribution in the human population, we observed consistent downregulation of ISM1 expression in asthma with a unimodal distribution." (PMID 37932719, 2023). "To explore the potential role of ISM1 in asthma, we conducted an analysis of human RNA-Seq data from the Genotype-Tissue Expression B37 and B38_GC33 projects using Ingenuity Pathway Analysis (IPA) (OmicsSoft, Qiagen)." (PMID 37932719, 2023). "We conducted a comparative transcriptomic analysis of WT and ISM1−/− mouse lung tissue at baseline to understand the mechanism of ISM1’s anti-inflammatory function in asthma." (PMID 37932719, 2023). "Collectively, these findings suggest that ISM1 may be critical in limiting airway inflammation in asthma." (PMID 37932719, 2023). "ISM1−/− mice may thus be useful in studying asthma-COPD overlap syndrome, whose molecular mechanisms remain poorly studied." (PMID 37932719, 2023). "Interestingly, in contrast to asthma conditions, our earlier study found that ISM1 expression was upregulated in an LPS-induced acute lung injury mouse model." (PMID 37932719, 2023). "However, whether ISM1 plays a role in the pathogenesis of asthma remains unknown." (PMID 37932719, 2023). "This study revealed for the first time that ISM1 functions to restrain airway hyperresponsiveness to HDM-triggered allergic-like airway/lung inflammation in mice, consistent with its persistent downregulation in human asthma." (PMID 37932719, 2023).
Autoimmunity (1 paper, 2025). The occurrence of an immune reaction against the organism's own cells or tissues. "These pathways are integral to autoimmunity and chronic inflammation, reinforcing the relevance of ISM1 suppression in autoantibody-positive RA." (PMID 40506888, 2025).
cardiac hypertrophy (1 paper, 2024). "ISM1 lost its protective effects against cardiac hypertrophy and fibrosis after SIRT1 deficiency." (PMID 38300636, 2024). "Besides, ISM1 lost its protective effects against cardiac hypertrophy and remodeling after AKT i treatment." (PMID 38300636, 2024). "Then we investigated whether ISM1 overexpression improved cardiac hypertrophy and interstitial fibrosis in aging hearts." (PMID 38300636, 2024). "Furthermore, disruption of ISM1 accelerated cardiac hypertrophy and fibrotic remodeling in aging hearts." (PMID 38300636, 2024).